ZEB1 (zinc finger E-box binding homeobox 1)
Diseases named in the same sentence as ZEB1 in open-access papers (continued):
Sharing a sentence is not in itself a finding about the gene and the disease.
adenocarcinoma (7 papers, 2015 to 2023). A common cancer characterized by the presence of malignant glandular cells. "In primary adenocarcinoma of the colon, IL-6R expression has been positively correlated with EMT-associated mesenchymal markers SNAIL, SLUG, VIM, ZEB1, and ZEB2." (PMID 31741710, 2019). "In a human adenocarcinoma panel, H2A.X levels correlate inversely with Slug and ZEB1 levels." (PMID 26876487, 2016). "Also we observed elevated expression level of mesenchymal markers including Snail, Zeb1 and Vimentin in matched lung tumors from adenocarcinoma patients compared to normal adjacent tissues." (PMID 25970786, 2015). "ZEB1 is upregulated at the invasive front of CRC, primarily in the stromal cells, whereas expression in the dedifferentiated adenocarcinoma cells is discrete." (PMID 28552992, 2017).
colorectal (7 papers, 2017 to 2022). "Further, we investigated the interactions between RUNX3 and ZEB1 and the involvement of the interactions between RUNX3 and ZEB1 in chronic lung injury induced by long-term exposure to MA." (PMID 36479199, 2022).
neurodegenerative disease (7 papers, 2009 to 2025). A disorder of the central nervous system characterized by gradual and progressive loss of neural tissue and neurologic function. "Fused in sarcoma, an RNA-binding protein linked to neurodegenerative diseases acts through miR-200c and its target transcript ZEB1." (PMID 36402997, 2022).
neurological disorders (4 papers, 2022 to 2025). "Loss of ubiquilin 1, a protein critical for combating neurological disorders linked to protein aggregation, significantly increases the expression of ZEB1." (PMID 36402997, 2022). "Among these, 31 were up-regulated and 75 were down-regulated in NP rats compared with sham rats, such as nervous system disease-related genes Zeb1, Atf3, Vip, and Aurkb." (PMID 40485981, 2025). "Furthermore, we provide a comprehensive review of the current knowledge regarding the potential roles of ZEB1 in neurological disorders." (PMID 36402997, 2022). "ZEB1 as a focal transcription factor of EMT has been considered a potential target for the prognosis and treatment of various neurological diseases." (PMID 36402997, 2022).
benign neoplasm (3 papers, 2015 to 2025). A neoplasm which is characterized by the absence of morphologic features associated with malignancy (severe cytologic atypia, tumor cell necrosis, and high mitotic rate). "Similarly, the overexpression of ZEB1 and TWIST was observed in malignant prostatic cancer as compared to benign tumors." (PMID 39941895, 2025).
inflammation (3 papers, 2023 to 2025). Aberrant reaction of the microcirculation characterized by movement of fluid and leukocytes from the blood into extravascular tissues. "In summary, we hypothesized that the upregulation of ZEB1 expression in human periapical inflammation promotes Th17 cell activation, and ZEB1 transcription is closely associated with the activation of p-STAT3." (PMID 40016707, 2025). "We questioned whether the role and mechanism of action of ZEB1 in the regulation of acute inflammation and immunosuppression are conserved in the context of chronic autoimmune inflammation." (PMID 37978290, 2023). "Simultaneously, ZEB1 induces autophagy to eliminate damaged mitochondria, and other organelles, thereby preventing excessive inflammation that could lead to cell and tissue damage or contribute to the development of chronic inflammation." (PMID 37978290, 2023).
hematological malignancies (2 papers, 2024 to 2025). "Although the function of the ubiquitinated TRIM26 protein has not yet been studied in the context of hematological malignancies, the importance of the USP39/ZEB1/TRIM26 axis deserves to be investigated in the context of MM." (PMID 39736693, 2024).
CNS disorders (1 paper, 2025). "Targeting ZEB1 may offer a novel therapeutic approach for controlling neuroinflam-mation and preserving neurogenesis in central nervous system disorders." (PMID 41148802, 2025).
renal diseases (1 paper, 2023). "To date, no studies were found showing the relationship between VitD deficiency and ZEB1/2 regulation in renal diseases." (PMID 37391399, 2023).
respiratory disorder (1 paper, 2022). "ZEB1 overexpression in a mouse model indicated lack of ZEB1 is associated with greater mortality during the perinatal period due to severe T-cell insufficiency, respiratory disorder, and skeletal deficiency." (PMID 36402997, 2022).
ZEB1 also shares sentences with these, for which no sentence is quoted: idiopathic pulmonary fibrosis (4 papers); intrahepatic cholangiocarcinoma (3); oral submucous fibrosis (3); tongue squamous cell carcinoma (3); actinic keratosis (2); acute lymphoblastic leukemia (2); chronic pancreatitis (2); classical Hodgkin lymphoma (2); corneal disease (2); cutaneous squamous cell carcinoma (2); endometrial adenocarcinoma (2); esophagitis (2); latent infection (2); liver cirrhosis (2); malignant mesothelioma (2); oral cavity carcinoma (2); abortion (1); anovulation (1); bladder transitional cell carcinoma (1); blood cancers (1); bone disorder (1); bone metastasis (1); brain injury (1); brittle cornea syndrome type 1 (1); bronchioalveolar carcinoma (1); cardiac disease (1); cardiovascular disease (1); cerebrovascular diseases (1); chlamydial infection (1); chordoma (1).
A further 70 diseases each share a sentence with ZEB1 in 1 paper.